LCK (LCK proto-oncogene, Src family tyrosine kinase)
Diseases named in the same sentence as LCK in open-access papers (continued):
Sharing a sentence is not in itself a finding about the gene and the disease.
oral cancer (6 papers, 2017 to 2024). "LCK is an important factor regulating the motility of oral cancer cells and is associated with the invasion and metastasis of oral cancer cells." (PMID 35480305, 2022). "Last but not least, we performed immunohistochemical analyses using four tissue samples from oral cancer patients in order to investigate LCK protein expression and localization within the primary tumor as well as in tumor-infiltrating lymphocytes." (PMID 34116687, 2021). "Analysis of invasive heterogeneity led to the discovery of LCK as an important regulator of motility in oral cancer cells." (PMID 34116687, 2021). "While our study provides strong in vitro evidence for a function of LCK in oral cancer cell migration and invasion, additional in vivo experiments are necessary to establish LCK as a relevant and druggable target to prevent cancer metastasis." (PMID 34116687, 2021). "By isolating individual subclones of a highly invasive oral cancer cell line, we identified the Lymphocyte cell-specific protein-tyrosine kinase (LCK) as an important regulator of migration and invasion." (PMID 34116687, 2021). "Our observation of significant epigenetic upregulation of TRPM2 and LCK is consistent with earlier reports on oral cancer and oral lichen planus (oral pre-cancer)." (PMID 31796082, 2019). "Up- and down-regulation of several genes in our samples corroborate with their protein expression, including actionable gene such as LCK, in oral cancer tissues from TCGA database." (PMID 28886030, 2017). "A.770041 inhibits LCK activity and blocks the invasion of oral cancer cells." (PMID 37891201, 2023). "Hence, inhibition of LCK in oral cancer cells has the potential to modulate cancer cell plasticity by inducing differentiation to a less malignant state." (PMID 34116687, 2021). "Since our integrative expression analyses in combination with functional in vitro cell line data suggested an important role of LCK in modulating oral cancer cell aggressiveness, we wanted to analyze the expression and prognostic relevance of LCK in more detail." (PMID 34116687, 2021). "Hence, small molecule mediated inhibition of LCK could be a promising anti-metastasis therapy option for oral cancer patients." (PMID 34116687, 2021). "Moreover, phosphoproteomics as well as protein interaction studies should be performed to identify key substrates of LCK, which will enable a deeper mechanistic understanding of the signaling pathways involved in LCK-dependent differentiation and invasion of oral cancer cells." (PMID 34116687, 2021). "Interestingly, LCK mRNA as well as protein expression strongly and significantly correlated with the invasion factor specifically in the Vimhigh/N-cadhigh subgroup of clones, which further supports the idea that LCK is an important factor of oral cancer cell motility." (PMID 34116687, 2021). "Since LCK is a druggable enzyme, we focused on this non-receptor tyrosine kinase to more closely investigate its biological role and target potential in the context of oral cancer cell migration, invasion and metastasis." (PMID 34116687, 2021).
prostate carcinoma (6 papers, 2019 to 2024). A carcinoma that arises from epithelial cells of the prostate gland. "Genes in NK cells (i.e., BCL11B for T-ALL, MAP3K7IP2 for prostate cancer) and in monocytes (i.e., LCK and BCL11B for T-ALL, PDCD1LG2 for Hodgkin’s lymphoma, PRDM16 for AML, CACNA1D for prostate cancer) were found significant in our meta-EWAS." (PMID 38466776, 2024). "In a nitroproteomic study, researchers found that lymphocyte-specific protein tyrosine kinase (LCK), a key factor involved in T-cell activation, is nitrated and subsequently inactivated by MDSC-derived reactive nitrogen species (RNS) in a mouse model of treatment-resistant prostate cancer." (PMID 33643299, 2020).
acute myeloid leukemia (5 papers, 2017 to 2023). Acute myeloid leukemia (AML) is a group of neoplasms arising from precursor cells committed to the myeloid cell-line differentiation. "A recent study reported that mutated and overexpressed LCK promoted the proliferation of acute myeloid leukemia cell lines." (PMID 31672930, 2019). "Mining of RNA-seq data showed that LCK was expressed in primary diffuse large B-cell lymphoma (DLBCL) as well as acute myeloid leukemia (AML)." (PMID 36711753, 2023). "Several studies have reported high levels of LCK expression in acute myeloid leukemia." (PMID 29062038, 2017). "Several studies have demonstrated a role of LCK in acute myeloid leukemia." (PMID 29062038, 2017).
colorectal cancer (5 papers, 2019 to 2025). A primary or metastatic malignant neoplasm that affects the colon or rectum. "Several data cohorts revealed that high LCK expression was associated with favorable survival in patients with blood, lung, skin, and ovarian cancer, but it was poor in colorectal cancer." (PMID 36430477, 2022). "This dependence on UNC119 for proliferation has previously been shown in colorectal cancer cell lines, which rely on LCK signalling considerably less than T-ALL cells do." (PMID 39814552, 2025).
diabetes (5 papers, 2020 to 2024). "CD247 and LCK have both been previously linked to diabetes and which could warrant further investigation." (PMID 33933144, 2021). "In this study, we observed the enrichment effect of LCK on key pathways related to diabetes, such as the PI3K signaling pathway and the inflammatory response pathway." (PMID 35187175, 2022). "In summary, we used a publicly available GEO dataset to perform WGCNA of immune cell infiltration in the context of diabetes and systematically identified a module related to clinical features and four hub genes (CSF1R, H2AFV, LCK, and TLR9) that may be associated with T2DM." (PMID 35187175, 2022). "Then, four hub genes related to the occurrence and development of diabetes were selected from the brown module: CSF1R, H2AFV, LCK, and TLR9." (PMID 35187175, 2022). "Thus, LCK, TLR9, CSF1R, and H2AFV are suggested to play important roles in immune infiltration in subjects with diabetes." (PMID 35187175, 2022). "Thus, LCK, TLR9, CSF1R, and H2AFV are suggested to play an important role in the metabolism of patients with diabetes." (PMID 35187175, 2022).
diffuse large B-cell lymphoma (5 papers, 2016 to 2023). "Moreover, LCK expression positively correlated with the levels of infiltrating B cells in diffuse large B‐cell lymphoma (DLBCL) and GBM." (PMID 32237064, 2020).
glioblastoma multiforme (5 papers, 2020 to 2022). "Recently, a pro-migratory effect of LCK was observed in glioblastoma, which has been linked to an increased phosphorylation of Paxillin on tyrosine 118, an important post-translational modification associated with migration and focal adhesion turnover." (PMID 34116687, 2021). "Interestingly, LCK was found to be significantly increased in the glioblastoma cells U-251." (PMID 32110969, 2020).
ovarian carcinoma (5 papers, 2021 to 2024). A malignant neoplasm originating from the surface ovarian epithelium. "Our study defines the mechanistic impact of LCK and potentially other non-receptor tyrosine kinases in regulation of HR repair that is apparently crucial to ovarian cancer’s response to chemotherapy and PARP inhibitors." (PMID 37370140, 2023).
atherosclerosis (4 papers, 2022 to 2024). A disease characterized by the build-up of fatty material and calcium deposition in the arterial wall resulting in partial or complete occlusion of the arterial lumen. "In addition, LCK was reported to inhibit heat shock protein 65-mediated reverse cholesterol transport in T cells, which is involved in one of the causes of atherosclerosis." (PMID 36316672, 2022). "LCK inhibitor attenuates the development of atherosclerosis and promotes plaque stability." (PMID 36316672, 2022).
Autoimmunity (4 papers, 2017 to 2025). The occurrence of an immune reaction against the organism's own cells or tissues. "To understand how the P440S LCK variant impacts thymic T cell development, T cell effector and regulatory functions, and the development of autoimmunity/inflammation, we used a knock-in mouse model of the human variant." (PMID 37962568, 2024). "DUSP22 also participates in the inactivation of the LCK (lymphocyte-specific protein tyrosine kinase) pathway, resulting in reduced immunity and autoimmunity mediated by T-cells." (PMID 37627126, 2023). "PTPN22 downregulates this LCK action and thus TCR signaling, and its inhibition can lead to increased risks for autoimmunity." (PMID 28081217, 2017).
pancreatic cancer (4 papers, 2020 to 2024). "In addition, future studies are needed to determine the degree of TRPM8 multimerization mediated by LCK is positively correlated with the severity of pancreatic cancer in clinical patients." (PMID 35665750, 2022). "Our findings demonstrate that the LCK-14-3-3ζ-TRPM8 axis for regulates TRPM8 assembly, channel function, and LCK activity and maybe provide potential therapeutic targets for pancreatic cancer." (PMID 35665750, 2022).
thymoma (4 papers, 2020 to 2022). A neoplasm arising from the epithelial cells of the thymus. "Robert J and co-workers showed that mislocalization of LCK impaired thymocyte differentiation and promoted thymoma development; this brought forward LCK’s localization to specific cellular compartments, which is vital for its function." (PMID 36430477, 2022). "Survival analysis revealed that thymoma patients with high LCK or RORC expressions had favorable clinical outcomes." (PMID 34778027, 2021). "The results from both UALCAN and TCPA showed that LCK expression was higher in thymoma and DLBCL." (PMID 32237064, 2020). "Our results showed that LCK expression was the highest in thymoma and DLBCL, whereas it was lower in GBM, LGG, and ACC, and the lower LCK expression in DLBCL and GBM predicted poor survival." (PMID 32237064, 2020). "Interestingly, LCK and CD3E had a generally positive correlation with those eight immune checkpoint genes for pan-cancers, except for thymoma." (PMID 35004669, 2021).
type 1 diabetes (4 papers, 2022 to 2025). "It has been reported that βig-h3 inhibits T cell activation in type 1 diabetes via suppression of LCK." (PMID 36568106, 2022). "A recent study revealed that the G allele of SNP rs10914542 of LCK inhibits the TCR/CD3-mediated T cell activation and increases the risk of type 1 diabetes in children." (PMID 36568106, 2022).
bladder cancer (3 papers, 2020 to 2024). "LCK, as a major TCR kinase, is associated with improved overall survival in bladder cancer patients treated with immunotherapy." (PMID 39033098, 2024). "Moreover, FN1, CXCL12, CD3E, LCK, and ZAP70 were key interconnected node genes in PPI networks and are also associated with overall survival in patients with bladder cancer." (PMID 33204728, 2020). "In conclusion, we have developed and validated a novel tumor-specific T cell signature (including VAMP5, TIGIT, LCK, CD27, and CACYBP) as a prognostic biomarker for bladder cancer patients treated with immunotherapy using single cell multi-omics data." (PMID 39033098, 2024). "We developed a five-gene signature (including VAMP5, TIGIT, LCK, CD27 and CACYBP) based on tumor-specific T cell-related genes to predict the immunotherapy response in bladder cancer patients." (PMID 39033098, 2024). "Two bladder cancer cohorts (GSE176307 and IMvigor210) receiving immunotherapy were recruited to validate the prognostic value of LCK and CD3E for immunotherapy." (PMID 35004669, 2021). "Immunohistochemical staining showed a consistent expression trend of LCK and CD3E between normal tissue and bladder cancer samples." (PMID 35004669, 2021). "Therefore, our study aimed to investigate the role of tumor-specific T cells in bladder cancer immunotherapy by constructing TstcSig, consisting of five tumor-specific T cell-related genes: CD27, CACYBP, TIGIT, LCK, and VAMP5." (PMID 39033098, 2024). "Furthermore, Kaplan-Meier survival analysis revealed that the higher expression of VAMP5, TIGIT, LCK, CHORDC1, CD27, and CACYBP was correlated with better outcomes in bladder cancer patients treated with immunotherapy." (PMID 39033098, 2024).
cervical cancer (3 papers, 2023 to 2025). A primary or metastatic malignant neoplasm involving the cervix. "Based on research on LCK in other types of tumors, we speculate that LCK may be associated with immune evasion in the inflammation-related cervical cancer risk model." (PMID 38903179, 2024).
cutaneous melanoma (3 papers, 2017 to 2022). A primary melanoma arising from atypical melanocytes in the skin. "A few other studies also demonstrated that cutaneous melanomas from the immune transcriptomic subgroup that correlates with pathological lymphocytic infiltration also express elevated levels of LCK protein, which are associated with improved patient survival." (PMID 33490091, 2020). "Furthermore, Because LCK was the most important prognostic factor in cutaneous melanoma, the negative correlation between HRAS and LCK at transcriptional level indicates that HRAS might be a critical molecule in cutaneous melanoma." (PMID 29349077, 2017).
endometrial cancer (3 papers, 2016 to 2022). Primary or metastatic malignant neoplasm involving the endometrium (mucous membrane that lines the endometrial cavity). "For example, we discovered that LCK is a candidate therapeutic gene in endometrial cancer, and the expression level of LCK was significantly correlated with a somatic alteration of chr10:82187096." (PMID 26716509, 2016). "We downloaded immune metagene and functional data of patients with different subtypes of endometrial cancer from The Cancer Genome Atlas database and selected the lymphocyte-specific kinase (LCK) metagene as a representative genetic marker of the immune microenvironment in endometrial cancer." (PMID 33159014, 2020).
endometrioid tumor (3 papers, 2017 to 2025). A benign, borderline, or malignant epithelial tumor of the female reproductive system characterized by the presence of glands and/or cysts lined by neoplastic cells that resemble endometrial cells. "CD55 was found to be highly expressed in CSCs in endometrioid tumors, and it can induce DNA repair through ROR2/JNK and lymphocyte-specific protein tyrosine kinase (LCK) signaling, leading to cisplatin resistance." (PMID 39919692, 2025).
lymphocytic leukemia (3 papers, 2021 to 2022). "LCK belongs to the Src family of tyrosine kinases and has been best studied in the context of T-cell function and signaling as well as lymphocytic leukemia of the B-cell lineage." (PMID 34116687, 2021). "Moreover, inhibition of LCK activity sensitizes lymphoid leukemia cells to GCs, whereas its mechanism is largely uncharacterized." (PMID 36490346, 2022). "LCK (lymphocyte-specific protein tyrosine kinase) belongs to the SRC family of tyrosine kinases and has been best studied in the context of T-cell function and signaling as well as lymphocytic leukemia of the B-cell lineage." (PMID 36341345, 2022).
periodontitis (3 papers, 2021 to 2023). An acute or chronic inflammatory process that affects the tissues that surround and support the teeth. "This means that FYN, LYN and LCK, which are highly expressed, play an important role in the imbalance of the immune system of periodontitis." (PMID 33841510, 2021).
primary immunodeficiency (3 papers, 2019 to 2023). "In this study, we have identified four enriched crosstalk genes in primary immunodeficiency, Interferon type I signalling, and translation factors pathways; that is, LCK, PTPRC, EIF4A1, and EIF4EBP1." (PMID 37277696, 2023). "Enrichment Kyoto Encyclopedia of Genes and Genomes (KEGG) analysis revealed DEGs engaged into three metabolic pathways: NF-kappa B signaling pathway (ZAP70, LCK, LTB), T cell receptor signaling pathway (ITK, ZAP70, LCK), and primary immunodeficiency (ZAP70, IL7R, LCK)." (PMID 30917529, 2019).
psoriasis (3 papers, 2019 to 2022). An autoimmune condition characterized by red, well-delineated plaques with silvery scales that are usually on the extensor surfaces and scalp. "Inhibitors of LCK have been reported to be efficacious in T cell-driven inflammatory diseases that include psoriasis, multiple sclerosis, lupus, and arthritis." (PMID 36144198, 2022). "We also identified 36 KDs that were shared across multiple psoriasis supersets and tissue-specific regulatory networks, such as LCK and STAT1." (PMID 30642337, 2019).
T-cell lymphoma (3 papers, 2006 to 2023). "A body of evidence suggests that HIV-1 proviruses integrated into several oncogenes, such as signal transducer and activator of transcription 3 (STAT3) and lymphocyte-specific protein tyrosine kinase (LCK), thus paving the way for developing T-cell lymphomas 5,65,66." (PMID 37645926, 2023).
acute lymphoblastic leukemia (2 papers, 2023 to 2025). Leukemia with an acute onset, characterized by the presence of lymphoblasts in the bone marrow and the peripheral blood. "Moreover, as LCK is a driver in T acute lymphocytic leukaemia, it is important to understand its regulation." (PMID 39814552, 2025). "UNC119 may therefore represent a novel therapeutic target in T acute lymphocytic leukaemia, which alters the subcellular localisation of LCK in T acute lymphocytic leukaemia cells but preserves the function of existing cytotoxic lymphocytes." (PMID 39814552, 2025).
Allergy (2 papers, 2009 to 2025). An allergy is an immune response or reaction to substances that are usually not harmful. "Notable genes associated with allergy, immune responses, and inflammation were found (LCK, BACH2, SATB1, LIME1, KSR1, BCL11B, TCF1, and EVL)." (PMID 41394805, 2025).
Alzheimer disease (2 papers, 2024 to 2025). A progressive, neurodegenerative disease characterized by loss of function and death of nerve cells in several areas of the brain leading to loss of cognitive function such as memory and language. "Conversely, for hub genes identified from upregulated DEGs, Alzheimer’s disease has been linked to CD2, CDC25A, CKS2, LCK, PRKACG, and S100A7." (PMID 39766348, 2024). "In addition, studies have uncovered the molecular interactions between compounds derived from Sanghuangporus and Alzheimer’s disease; within Sanghuangporus, 374 disease-related targets have been identified, including crucial ones such as JAK1, LCK, MAPK1, STAT3, and STAT1." (PMID 39997416, 2025).
anaplastic large cell lymphoma (2 papers, 2006 to 2025). Anaplastic large cell lymphoma (ALCL) is a rare and aggressive peripheral T-cell non-Hodgkin lymphoma, belonging to the group of CD30-positive lymphoproliferative disorders, which affects lymph nodes and extranodal sites. "Additionally, several anaplastic large cell lymphomas (ALCL), of T cell origin, from PWH were found to have clonal proviral integrations in both STAT3 and the first intron of the src family tyrosine kinase LCK." (PMID 40627772, 2025).
breast tumor (2 papers, 2013 to 2020). "LCK is expressed not only in T cells but also in normal breast tissues and breast tumor samples." (PMID 24155921, 2013).
central nervous system lymphoma (2 papers, 2020 to 2021). "Given her continued lack of improvement, MSK-IMPACT was performed on the CSF and resulted in the discovery of MYD88, CD58, HIST1H1C, KMT2D, and LCK mutations suggestive of a lymphoid malignancy like primary central nervous system lymphoma (PCNSL)." (PMID 34729485, 2021).